MC4R (melanocortin 4 receptor)
Diseases named in the same sentence as MC4R in open-access papers (continued):
Sharing a sentence is not in itself a finding about the gene and the disease.
Obesity (continued). "Recently, melanocortin-4 receptor (MC4R) has been reported to be associated with the risk of obesity by the Genome-Wide Association Study (GWAS)." (PMID 31781208, 2019). "Previous studies demonstrated several MC4R variants and common genetic polymorphisms near the MC4R gene contributing to common obesity." (PMID 31429705, 2019). "Fat mass and obesity-associated gene (FTO) has been widely linked to obesity among populations, and posterior replications have shown an additional signal in the melanocortin 4 receptor (MC4R) locus." (PMID 31354816, 2019). "MC4R has an important role in energy homeostasis and appetite and is the main genetic cause of obesity in humans and animals." (PMID 32133054, 2019). "Melanocortin 4 receptor (MC4R) gene polymorphisms were detected to be associated with different levels of obesity." (PMID 31429705, 2019). "In contrast, we found that GoF MC4R variants were strongly associated with lower BMI (p = 2 × 10−47) and lower odds of obesity (p = 3 × 10−38), severe obesity (p = 1 × 10−09), type 2 diabetes (p = 4 × 10−06), and coronary artery disease (p = 0.02)." (PMID 31002796, 2019). "Here, the authors characterized 61 MC4R variants identified in 0.5 million people from the UK Biobank and examined the associations of these variants with BMI and obesity-related cardiometabolic diseases." (PMID 31686269, 2019). "Chronic exposure of pregnant mice to TBBPA inhibited the transcriptional activity of TSH-releasing hormone and melanocortin receptor 4 (MC4R) in the hypothalamus, which is a major regulator of energy homeostasis, with its mutations causing obesity." (PMID 30881345, 2019). "The PCS also highlighted several other highly scoring candidates with known causal roles in relation to diabetes and obesity such as MC4R (PCS = 0.43), WFS1 (0.41), ABCC8 (0.37), LEP (0.27), GCK (0.24) and HNF1A (0.23)." (PMID 30914061, 2019). "Compared with the normal weight group, rs2331841 of the MC4R gene was associated with obesity (P=0.032)." (PMID 31781208, 2019). "Gain-of-function genetic variants in the Melanocortin-4 Receptor associated with protection against obesity exhibit signaling bias for the recruitment of β-arrestin rather than canonical Gαs-mediated cAMP production." (PMID 31002796, 2019). "The common rs17782313 MC4R gene polymorphism was associated with obesity in both European adults and children showing a synergistic effect with FTO gene on obese phenotype." (PMID 30338250, 2018). "In this regard, free androgen levels in women with PCOS my correlate with obesity abnormalities.Additionally, the main reason for genetic obesity in human is mutation in melanocortin-4 receptor(MC4R) gene." (PMID 34466430, 2018). "In studies of European populations with severe obesity, the prevalence of heterozygous damaging MC4R mutations is ~ 6% and ~ 2% in children and adults, respectively, signifying the different etiologies of childhood and adult obesity." (PMID 30442103, 2018). "Obesity caused by damaging mutations in LEP and LEPR display an autosomal recessive mode of inheritance while obesity caused by MC4R mutations exhibit variable penetrance (recessive or co-dominant)." (PMID 30442103, 2018). "While loss-of-function mutations in MC4R cause familial forms of obesity, two rare gain-of-function MC4R polymorphisms have been identified that are associated with protection against obesity." (PMID 30068297, 2018). "In comparison, the prevalence of heterozygous MC4R mutations is 3–5% in Caucasian populations with early-onset obesity." (PMID 30442103, 2018). "In fact, heterozygous loss-of-function MC4R mutations have been shown to be the most common known genetic cause of human obesity." (PMID 30068297, 2018). "Another study that assessed the same polymorphism of MC4R gene highlighted a significant association with obesity in Mexican children." (PMID 30338250, 2018).
Obesity (continued). "It has been suggested that the varying onset and severity of obesity in heterozygous MC4R mutation carriers are related to the severity of the functional effects of the mutations." (PMID 30068297, 2018). "The rs12970134 and rs17782313 polymorphisms of the MC4R gene were identified to be associated with child and adult obesity, respectively in both Asian and European populations." (PMID 30338250, 2018). "Rarely, mutations in MC4R gene leading to function loss can lead to monogenic forms of obesity, but MC4R-linked obesity is better defined as a particular form which stands between rare recessive monogenic obesity forms and common polygenic ones." (PMID 30338250, 2018). "The artificial distinction between rare monogenic obesity and common polygenic obesity is now obsolete with the identification of MC4R variants of strong effect in the general population." (PMID 30121879, 2018). "The huge number of pathogenic heterozygous inactivating MC4R mutations are the most frequent genetic cause of obesity in humans." (PMID 29910730, 2018). "MC4R variation was recognised relatively early as a monogenic cause of severe obesity, accounting for as much as 6% of people with early onset obesity." (PMID 30121879, 2018). "The study based on meta-analysis of the European population, on the other hand, provided evidence for the association between the MC4R polymorphisms and the risk of obesity." (PMID 29315078, 2018). "Overexpression of AGRP in the mouse results in obesity and targeted inactivation of the MC4R causes obesity with features similar to the agouti obesity syndrome." (PMID 29843787, 2018). "A large study performed on 1,685 obese and normal-weight Mexican children found nominal associations between different gene polymorphisms, like those in ENPP1 rs7754561 and MC4R rs17782313, and obesity risk or BMI." (PMID 30338250, 2018). "The MC4R variant rs17782313 was the second gene that was positively associated with common obesity traits." (PMID 29679223, 2018). "The aim of the current study was to examine the prevalence of damaging LEP, LEPR, and MC4R mutations in Pakistani families having a recessive heritance of early-onset obesity." (PMID 30442103, 2018). "MC4R mutations are the most common known genetic cause of obesity, affecting 2–3% of the population in various cohorts tested." (PMID 30068297, 2018). "In other words, is SDV able to reverse the obesity phenotype associated with the Mc4r deficiency and bring the weight of the mice back to that of the normal weight of the control background strain (C57BL/6J)." (PMID 29545738, 2018). "The researchers investigated the role of Melanocortin-4 receptor (MC4R), gene variant and resistein levels with obesity." (PMID 30066661, 2018). "A study performed on newborns in Greece assessed both risk FTO and MC4R variants and concluded that approximately 80% of the Greek population are genetically predisposed to obesity development further on in life." (PMID 30338250, 2018). "Heterozygous loss-of-function MC4R mutations are the most common known genetic cause of monogenic human obesity, with more than 200 mutations described to date, affecting 2–3% of the population in various cohorts tested." (PMID 30068297, 2018). "The SNP rs17782313, mapped downstream of the MC4R gene, has been associated with body weight and obesity." (PMID 29686896, 2018). "Other studies of the same population revealed association between the MC4R C allele and food energy intake, which was regarded as a factor directly related to an elevated risk of obesity." (PMID 30271660, 2018). "Recently, setmelanotide (Rhythm Pharmaceuticals, Boston, Massachusetts, USA) has been developed as a novel MC4R agonist for the treatment of rare genetic disorders of obesity associated with defects in the MC4 pathway." (PMID 28739551, 2018). "This is in line with previous reports, showing a dramatically more consistent and severe obesity phenotype in homozygotes for MC4R mutations than in heterozygotes." (PMID 30068297, 2018).
Obesity (continued). "Consistent with others, our results indicate that the MC4R rs17782313 variant is positively associated with obesity traits in overweight/obese children." (PMID 29679223, 2018). "MC3R, like MC4R, is involved in energy homeostasis; while several human mutations have been identified, there is a less clear association with obesity for these mutations than for MC4R mutations." (PMID 28805746, 2017). "In total, four variants annotated as MC4R polymorphisms (all located downstream of the MC4R gene) have been found to be associated with obesity or BMI, including rs12970134, rs17782313, rs571312 and rs17700144." (PMID 28520814, 2017). "Mutations in the gene that encodes a protein called the melanocortin-4 receptor are the most common genetic cause of early onset obesity in children." (PMID 28829041, 2017). "In the current study, we investigated Asn274Ser non-synonymous mutation of the MC4R gene that has been linked to obesity in previous studies." (PMID 29937877, 2017). "Among the monogenic types of non-syndromic obesity, melanocortin-4 receptor (MC4R) deficiency is presumably the most frequent and the best understood form." (PMID 28218067, 2017). "A strong association was identified between MC4R rs17782313 genetic variant and risk of obesity in a European population which was then replicated in other populations, including Asian Indians." (PMID 29182660, 2017). "Subsequent to the fat mass and obesity associated (FTO) gene, the melanocortin 4 receptor (MC4R) gene was the second gene validated by the genome-wide association study (GWAS) for obesity." (PMID 28520814, 2017). "Recently, genome-wide association studies (GWAS) demonstrated MC4R to be one of the genes contributing to the etiology of common obesity." (PMID 28081251, 2017). "We performed the study to clarify the association of variants near MC4R gene with obesity-related phenotypes and gene-environment interactions in Chinese children and adolescents." (PMID 28081251, 2017). "Obesity-associated MC4R mutations confirm a role for MC4R-mediated signaling in human energy homeostasis." (PMID 29031731, 2017). "In fact, to this day MC4R mutations remain the most common monogenic form of obesity, with pathogenic mutations found in up to 5% of cases of severe childhood obesity and up to 1% of the general population with a BMI >30 kg/m2." (PMID 28013339, 2017). "The aim of this study was to evaluate the association of the FTO rs17817449 (G>T), GNB3 rs5443 (C825T) and MC4R Asn274Ser (A822G) gene polymorphism with obesity and obesity-related metabolic traits in Saudi subjects." (PMID 29937877, 2017). "Clinical studies have found that heterozygous Mc4r mutations confer protection from obesity-associated hypertension through reduced sympathetic tone." (PMID 28829041, 2017). "Observations of human polymorphisms highlight the Mc4r gene as one of the key genes for understanding obesity risk and its associated comorbidities." (PMID 28930194, 2017). "In thus far one of the largest cohorts of women with a history of GDM, we examined the associations of an obesity-associated MC4R variant with postpartum changes in body weight and glucose metabolism." (PMID 28852042, 2017). "Previous GWAS revealed that rs17782313 near the melanocortin 4 receptor (MC4R) gene was associated with increased risk of obesity in Europeans." (PMID 27926527, 2017). "MC4R has been extensively investigated in obesity research, and decreased activity of MC4R is the leading monogenic cause of severe early onset obesity." (PMID 28805746, 2017). "The prominent role of Mc4r in the hypothalamic regulation of energy balance has been confirmed in humans, in whom the Mc4r mutation leads to one of the most common forms of monogenic obesity." (PMID 28690493, 2017). "We conclude that in contrast to the human it is rather unlikely that the MC4R gene is significantly associated with predisposition to obesity across all dog breeds." (PMID 28755272, 2017).
Obesity (continued). "Heterozygous loss of function (LOF) mutations in MC4R are found more frequently with prevalence estimates ranging from 1 to 5% in children or adults with severe obesity." (PMID 29031731, 2017). "The rs17782313 and rs12970134 variants, mapped 188kb and 154kb downstream of MC4R gene respectively, were found to be associated with BMI and obesity-related phenotypes in previous GWAS studies." (PMID 28081251, 2017). "In accordance with their role in anorexic signaling pathways, mutations in the MC4R and POMC genes, which encode the melanocortin 4 receptor and pro-opiomelanocortin, respectively, result in hyperphagia and obesity in humans and rodents." (PMID 28592656, 2017). "Polymorphisms near MC4R not only play an important role in the predisposition to obesity, but also affect eating behaviors directly." (PMID 28520814, 2017). "Pierwszy z nich ujawnił związek wariantu genu FTO (Fat mass- and Obesity-associated), w drugim etapie wykryto związek SNP w pobliżu genu MC4R." (PMID 29077558, 2017). "Haploinsufficiency of the melanocortin-4 receptor, the most common monogenetic obesity syndrome in humans, is associated with a reduction in autonomic tone, bradycardia, and incidence of obesity-associated hypertension." (PMID 28829041, 2017). "In the case of early onset of obesity, mutations in the melanocortin-4 receptor (MC4R) (D90N) gene are the most frequent monogenic causes of severe obesity and it has dominant negative effect on the WT-MC4R/D90N receptor heterodimer." (PMID 28062602, 2017). "We investigated the combined effect of physical activity, sedentary behaviors and MC4R variants on BMI and risk of overweight/obesity." (PMID 28081251, 2017). "Strong association between the MC4R gene and risk of obesity was identified by a genome-wide association (GWAS) study whereas the association between the Transcription Factor 7-Like 2 (TCF7L2) gene and risk of T2D was identified by a genome wide linkage study." (PMID 29182660, 2017). "In this study of a large cohort of Chinese women with a history of GDM, we found that the obesity-associated MC4R genotype was significantly related to greater reduction in HbA1c and 2-h OGTT levels during postpartum." (PMID 28852042, 2017). "Deletion of MC4R produces obesity and hyperphagia; furthermore, the most common syndromic cause of obesity, Prader–Willi, occurs in part due to reduced cleavage of POMC." (PMID 28572791, 2017). "MC4R mutations result in hyperphagia, early-onset obesity, increased linear growth in childhood, increased body fat and fat-free mass, increased bone mineral density, and hyperinsulinemia." (PMID 28218067, 2017). "MC4R knockout mice are severely obese while loss of one MC4R allele results in an intermediate obesity phenotype demonstrating that weight regulation is sensitive to quantitative variation in MC4R expression." (PMID 29031731, 2017). "Conversely, mutations in the POMC, MC3R, or MC4R genes cause common or massive early-onset obesity in humans, further supporting a crucial role for the melanocortin pathway in energy homeostasis." (PMID 28424580, 2017). "We validated the association between the polymorphism rs12970134 near MC4R and obesity, and found its association with childhood appetite (food responsiveness and satiety responsiveness) and beverage intake in overweight/obese children." (PMID 28520814, 2017). "In this regard, a recent work focused on the effect of the obesity-associated MC4R gene on metabolic syndrome has revealed a relevant gene-diet interaction with dietary patterns." (PMID 28829397, 2017). "Loss-of-function mutations in the human melanocortin type 4 receptor (MC4R) are associated with hyperphagia, severe early-onset obesity, increased longitudinal growth, fasting hyperinsulinemia, NAFLD and increased lean body mass." (PMID 28207798, 2017). "Recently, a mouse study described that the activation of Mc4r reduces food intake and increases energy expenditure, preventing obesity-associated increased adiposity." (PMID 28930194, 2017).
Obesity (continued). "The melanocortin-4 receptor (MC4R) regulates metabolism by modulating eating behavior and MC4R variants (rs17782313 and rs571312) are associated with obesity in Asians and Caucasians." (PMID 27213003, 2016). "With regards to MetS, MC4R is the largest known single risk factor for combined obesity and T2DM manifestation, as replicated by several GWAS studies." (PMID 27147943, 2016). "In contrast to genetic leptin or leptin receptor loss-of-function, which are extremely rare, heterozygous mutations in the melanocortin-4-receptor (MC4R) are the most common monogenic cause of obesity, accounting for around 6% of severe, early-onset obesity." (PMID 27899914, 2016). "We confirmed that there was a positive interaction between MC4R variants and energy intake which was associated with increased risk of obesity after adjusting for confounders." (PMID 27213003, 2016). "MC4R-knockout mice, and loss-of-function mutations in MC4R in humans, are associated with severe obesity and hyperinsulinemia, supporting an essential role for the melanocortin system in the regulation of glucose metabolism." (PMID 27626491, 2016). "Associations have also been observed between the genotype of a Single Nucleotide Polymorphism (SNP), rs17782313, near the MC4R gene and adult obesity." (PMID 26907388, 2016). "Results showed that MC4R deficiency led to a dramatic alteration in energy homeostasis including obesity and hyperglycaemia, whereas MC3R deficiency showed hypophagia and reduced body weight." (PMID 27713523, 2016). "Childhood obesity is known to have a strong genetic component, with mutations in the melanocortin-4 receptor (MC4R) gene being the most common monogenetic cause of obesity." (PMID 27738543, 2016). "There was relevant, but not quite significant (P = 0.594), interaction between energy intake and MC4R polymorphism in determining the risk of obesity after adjusting for confounders such as age, gender, area, total activity and smoking status (P = 0.0594)." (PMID 27213003, 2016). "Common and rare variants in the melanocortin-4 receptor MC4R locus 18q21.32 (rs74861148, rs483125, and rs11872992) or its promoter region were associated with triglycerides, obesity and T2DM." (PMID 27147943, 2016). "Sequence analysis also demonstrated a relatively high frequency of pathogenic mutations in the MC4R gene in individuals with severe early-onset obesity, which indicates that MC4R mutations are one of the most common monogenic causes of obesity in humans." (PMID 27072576, 2016). "The importance of the melanocortin system in obesity is illustrated by the fact that mutations of MC4R are the most common causes of monogenic obesity, leading to a phenotype of extreme adiposity." (PMID 27373214, 2016). "Here we investigated how FTO and MC4R gene variants linked with obesity relate to patterns of fetal growth and to placental FTO expression." (PMID 26907388, 2016). "The interaction of mental stress with MC4R significantly increased the risk of obesity: Korean adults with MC4R minor alleles had a higher risk of obesity in high stress states independent of other obesity related factors." (PMID 27213003, 2016). "Since there is only one copy of MC4R in our patient, this case supports haploinsufficiency as the cause of the obesity phenotype." (PMID 27738543, 2016). "For example, mutations in MC4R (which encodes melanocortin 4 receptor) cause a Mendelian form of severe obesity but have been proposed to predispose to adult-onset obesity under a complex trait model." (PMID 27855690, 2016). "We observed statistical differences in genotype frequencies of MC4R polymorphism among the normal-weight, overweight and obesity groups (p < 0.01)." (PMID 27213003, 2016). "According to these interactions, the association of MC4R genotypes and obesity was dependent on the energy intake." (PMID 27213003, 2016).